POM121L2 (POM121 transmembrane nucleoporin like 2)
Synonyms: POM121L; POM121-L
Tractability: No criterion of Open Targets' tractability assessment is met for any kind of drug.
Safety:
Unwanted effects reported when the protein is acted on. In parentheses: how it was acted on, where the effect was seen, and who reports it.
nausea and vomiting (source: ClinPGx)
Gene: Protein-coding gene on chromosome 6 (27,285,903 to 27,312,273, reverse strand). Ensembl gene ENSG00000158553.
Gene Ontology:
Molecular function: structural constituent of nuclear pore
Biological process: protein import into nucleus; RNA export from nucleus
Cellular component: nuclear pore
Genetic constraint (gnomAD): Loss-of-function variants: 1 observed, 1.79 expected, observed/expected ratio (o/e) 0.56, 90% interval 0.18 to 1.79. That is too few expected variants to judge how well the gene tolerates losing a copy. Missense variants: 1,167 observed, 1,299.8 expected, observed/expected ratio (o/e) 0.9, 90% interval 0.86 to 0.94. Synonymous variants: 459 observed, 499.87 expected, observed/expected ratio (o/e) 0.92, 90% interval 0.85 to 0.99.
Homologues: Orthologues: chimpanzee POM121L2 (98% identical), mouse Pom121l2 (49% identical), rat Pom121l2 (27% identical), zebrafish pom121 (24% identical), tropical clawed frog pom121 (19% identical), Drosophila melanogaster Nup153 (11% identical). Paralogues in human: POM121 (43% identical), POM121C (39% identical), NUP214 (21% identical), NPAP1 (19% identical), NUP153 (16% identical), POM121L12 (10% identical).
Diseases named in the same sentence as POM121L2 in open-access papers:
POM121L2 is named in the same sentence as 5 diseases in open-access papers, as found by Europe PMC text mining. Sharing a sentence is not in itself a finding about the gene and the disease. The quoted sentences say what the papers report.
schizophrenia (3 papers, 2016 to 2023). A major psychotic disorder characterized by abnormalities in the perception or expression of reality. "Variants in POM121L2 have been previously associated with risk for schizophrenia, and we did observe an enrichment of schizophrenia GWAS loci in the EA subset." (PMID 36940203, 2023). "A meta-analysis of 18 GWASs for schizophrenia supported involvement of the MHC region, TCF4, POM121L2, NOTCH4, AS3MT, CNNM2, and NT5C2." (PMID 27064909, 2016).
breast cancer (2 papers, 2020 to 2023). A primary or metastatic malignant neoplasm involving the breast. "Of these, three genes, namely POM121L2, KCNQ1, and CLEC4C, harbored significant methylation changes consistent with their differential expression in breast cancer." (PMID 33113958, 2020). "Of these, three genes, POM121L2, KCNQ1, and CLEC4C, harbored significant methylation changes consistent with their differential expression in breast cancer." (PMID 33113958, 2020).
triple-negative breast carcinoma (1 paper, 2020). An invasive breast carcinoma which is negative for expression of estrogen receptor (ER), progesterone receptor (PR), and human epidermal growth factor receptor 2 (HER2). "The POM121L2 gene codes for POM121 transmembrane nucleoporin like 2, which has been shown to be upregulated in triple negative breast cancer." (PMID 33113958, 2020).
POM121L2 also shares sentences with these, for which no sentence is quoted: autistic spectrum disorder (1 paper); Fibroadenoma (1).